RNU5F-2P (RNA, U5F small nuclear 2, pseudogene)
Gene: Small nuclear RNA gene on chromosome 1 (179,576,268 to 179,576,349, forward strand). Ensembl gene ENSG00000251875.
Homologues: Orthologues: chimpanzee U5 (99% identical), macaque U5 (90% identical), tropical clawed frog U5 (78% identical), tropical clawed frog U5 (77% identical), tropical clawed frog U5 (76% identical), zebrafish U5 (65% identical). Paralogues in human: RNU5F-3P (80% identical), RNU5F-7P (79% identical), RNU5E-10P (78% identical), RNU5E-6P (76% identical), RNU5F-4P (76% identical), RNU5B-2P (74% identical), RNU5E-4P (74% identical), RNU5F-6P (74% identical), RNU5A-8P (73% identical), RNU5E-8P (72% identical), RNU5E-7P (71% identical), RNU5A-4P (70% identical), and 13 more.